IL1B (interleukin 1 beta)
Diseases named in the same sentence as IL1B in open-access papers (continued):
Sharing a sentence is not in itself a finding about the gene and the disease.
viral infection (continued). "During viral infection, recognition of pathogen molecular associated patterns (PAMPs) by the cells, such as double stranded viral RNA, induces IL-1β mRNA expression and translation to generate the inactive form of the protein pro-IL-1β." (PMID 24788150, 2014). "Because IL-1β signals are associated with both host protection from viral infections and pathogenesis of inflammatory immune-mediated diseases, we here investigated the role of IL-1β-mediated signals in the development of TMEV-induced demyelinating disease." (PMID 22985464, 2012). "In the current study we have demonstrated that acute systemic poly I:C stimulation, mimicking systemic viral infection, was associated with significantly amplified CNS IL-1β and IFNβ responses in diseased animals compared to normal animals." (PMID 20399848, 2010). "For instance, IL-1β activates neutrophils and macrophages to clear pathogens, and inhibiting its function may increase the risk of bacterial or viral infections." (PMID 40520203, 2025). "Notably, inhibiting the release of mitochondrial reactive oxygen species and mitochondrial DNA reduces the IL-1β release associated with viral infection." (PMID 39728983, 2024). "IL-1β can have both direct and indirect antiviral effects in the context of other viral infections, but is also associated with a variety of pathological inflammatory disorders, including infections, autoimmunity, cardiovascular disease, and cancer (76, –, 79)." (PMID 39240187, 2024). "The inflammatory response to viral infection is heavily associated with IL-1β activities." (PMID 37376569, 2023). "It is usually a negative regulator of TLR3, and IL-1β consequently could reduce the antiviral defence function of the epithelium and cause an increase in viral infections susceptibility." (PMID 35469122, 2022). "NLRP3-dependent inflammasome assembly and consequent IL-1β activation has been shown to be pathogenic in several viral infections contributing to pulmonary fibrosis in cytomegalovirus infected mice and in patients with acute-on-chronic hepatitis B liver failure." (PMID 36189282, 2022). "During viral infection and replication, the “first signaling” for inflammasome activity comes from the activation of PRRs by pathogen-associated molecular patterns (PAMPs), leading to transcription of pro-IL-1β." (PMID 34310655, 2021). "Taking this into account, the beneficial effect of H9N2 virus infection on pulmonary pneumococcal clearance might partially be due to the induction of trained immunity associated with the enhanced IL-1β production." (PMID 33722928, 2021). "Interestingly, according to GO terms, a majority of these downregulated genes is associated with the host pro-inflammatory response to viral infection (e.g., Ccl2, IL-6, IL-1β)." (PMID 32231671, 2020). "During the first trimester of pregnancy, the acute immune activation due to maternal viral infection increases the risk for having autistic children, and, at the time of birth, elevated levels of IL-1β and IL-4 in mothers have been associated to a subsequent diagnosis of ASD." (PMID 31616420, 2019). "In contrast, the expression of IL-1B may be much lower in people who carry allele C, leading to weaker immune response during viral infection." (PMID 23927441, 2013). "Antagonists or neutralizers of IL1B, such as Canakinumab, could potentially reduce inflammation damage associated with viral infection." (PMID 22432004, 2012). "Despite many previous studies on the role of IL-1β signaling in viral infections, the underlying mechanisms of the signals involved in the protection from infection remain unclear." (PMID 22985464, 2012). "IL-1β causes some deleterious effects such as fever and anorexia, but has also been shown to contribute positively to the generation of adaptive immune responses induced by live virus infection." (PMID 23056330, 2012).
viral infection (continued). "After viral infection, pathogen-associated molecular patterns (PAMPs) in viral proteins and nucleic acids were recognized by host pathogen-recognition receptors (PRRs), such as Toll-like receptors (TLRs), which trigger gene expression and synthesis of the IL-1β precursor." (PMID 20614006, 2010). "Viral infection activates the immune system, leading to the release of inflammatory mediators such as proinflammatory cytokines (IL-6, IL-1β, and TNF-α) and eicosanoids (PG and LT)." (PMID 40580333, 2025). "These suggest that the production of NLRP3 inflammasome and its downstream effectors, caspase-1 and IL-1β, is positively correlated with the duration of viral infection." (PMID 40284982, 2025). "When mice were given MCC950 after viral infection, the levels of IL-1β and IL-18 in their bronchoalveolar lavage fluid were significantly reduced." (PMID 40906404, 2025). "IL-1β plays a pivotal role in innate immunity and is critically important for host defense against viral infections." (PMID 40673138, 2025). "NLRP4 can negatively regulate Tumor Necrosis Factor (TNF) and IL-1β-induced NF-κB activation, and can also negatively regulate type I interferon signaling in response to dsRNA, DNA, or viral infection, and regulate autophagy in response to bacterial infection." (PMID 41463370, 2025). "In the transcriptome data, Il1b and Ptgs2 (encoding cyclooxygenase 2, COX‐2) showed higher elevation at almost all the time points post viral infection, while some other genes like Il6, Il12b, and Cxcl5 only showed significant elevation at 48 hpi." (PMID 38992966, 2025). "Extracellular cleavage of IL-36 cytokines can be advantageous over intracellular processed IL-1β and IL-18 in response to viral infection." (PMID 40121229, 2025). "ST3GAL2 resists viral infection by downregulating pro-inflammatory cytokines (IL-6, IL-18, IL-1β, IFN-β, TNF-α) and upregulating anti-inflammatory cytokines (IL-4, IL-10, IL-13)." (PMID 40755778, 2025). "Incubation of neutrophils with IFNα and IFNγ resulted in gene expression changes that mimicked the cellular defence response to viral infection, whereas IL-1β and TNFα activated genes that are typically involved in the cellular response to bacterial infection." (PMID 41503139, 2025). "Glycoprotein indicators such as IL-1β, IL-8, IL-10, and IgM regulate fish immune response, represent innate immunity, and alter viral disease response." (PMID 41001068, 2025). "Chronic inflammation, triggered by factors such as viral infections, oxidative stress, and metabolic dysregulation, leads to the persistent activation of pro-inflammatory cytokines, including IL-1β, IL-17A, and TGF-β." (PMID 40607394, 2025). "AZM treatment led to significant reductions in the production of pro-inflammatory cytokines IL-1β, IL-6, and IL-8, which are often elevated during viral infections and contribute to epithelial damage." (PMID 40641604, 2025). "From an immunological perspective, vaccines and viral infections act as potent immune stimulants through activation of Toll-like receptors, antigen-presenting cells, and subsequent cytokine cascades, particularly IL-1β, IL-6, and TNF-α." (PMID 41155751, 2025). "This suggests that autonomous autoinflammation, tissue damage and viral infections at the end trigger a common inflammatory pathway employing the activation of inflammasomes and the activation of IL-1β." (PMID 38358415, 2025). "In humans, BCG vaccination induces reprogramming in monocytes through an IL-1β-dependent mechanism, leading to increased cytokine production and protection against experimental viral infection." (PMID 41087719, 2025). "Viral infection alone at 0–16 h after viral adsorption tended to increase IL1B mRNA levels, but they were decreased at 48 h." (PMID 40733507, 2025). "The rapid upregulation of IL-1β gene expression in response to viral infections is a well-documented phenomenon in mammalian studies, often observed as early as 6 hpi." (PMID 40959137, 2025).
viral infection (continued). "In future, broad tests with other pro‐inflammatory stimuli, such as cytokines (IFNγ, TNFα, and IL‐1β) and virus infection, are suggested." (PMID 39455284, 2025). "Together, by revealing the function and underlying mechanism of IL-1β on SARS-CoV-2-induced cell-cell fusion, our study highlights an unprecedented antiviral function for cytokines during viral infection." (PMID 39937682, 2025). "Inflammasomes were also enhanced by viral infection, as indicated by immunoblotting for mature IL-1β and cleaved caspase-1 P20." (PMID 38989466, 2024). "Inflammasome activation plays a role in the host defence against viral infection, whereby it activates caspase-1 and initiates the release of IL-1β." (PMID 38890537, 2024). "As expected, AZ reduced inflammatory cytokine expression, including TNF-α and IL-1β, and the translocation of NF-κB to the nucleus, which are all increased by viral infection." (PMID 38247540, 2024). "Normally, the canonical inflammasome pathway has been considered the mechanism for activating IL-1β upon viral infection." (PMID 39038050, 2024). "These include proinflammatory M1-like macrophages, which produce TNF, IL-1β and IL-6, in the context of both metabolic disease and viral infection." (PMID 39107476, 2024). "IL-1β is a potent proinflammatory cytokine produced as the first-line defense during viral infections." (PMID 39258253, 2024). "This suggests that, despite the general increase of IL-1β during viral infection, its expression is suppressed in the context of IAPA." (PMID 38651925, 2024). "PRV VP22 disrupts the binding between ZBP1 and RIPK3/Caspase-8 and inhibits the cleavage of Caspase-1 and IL-1β induction, thereby promoting viral infection." (PMID 39475237, 2024). "Emerging evidence suggests that ZBP1 activates the NLRP3 inflammasome during certain viral infections, leading to IL-1β production and inflammation (23, –, 25)." (PMID 39475237, 2024). "Viral infection induces a variety of proinflammatory cytokines and chemokines including IL-1b, IL-6, TNFa, CCL2, CCL3, CXCL1, CXCL2, CXCL9 and CXCL1034,35." (PMID 38750107, 2024). "Upon activation during viral infection, the virus coordinates the inflammatory response by secreting proinflammatory cytokines, particularly IL-1β." (PMID 39038050, 2024). "In order to further elucidate the effect of HST on the viral infection outcome in rare minnows, the mRNA levels of Hsp70, IL-1β, MyD88 and NF-κB in rare minnows were systematically monitored following GCRV challenge at Day 0, 2, 4, 6, 8 and 10 p.i.." (PMID 38932213, 2024). "IL-1β is a multifunctional inflammatory factor, which is essential for regulating the occurrence and development of viral diseases in poultry." (PMID 39376562, 2024). "Of note, ablation of AXL in mice has previously been shown to increase expression of type I IFN while impairing IL-1β production and T cell activation during viral infections." (PMID 39269281, 2024). "Severe viral infections often trigger the activation of inflammasomes, leading to the release of the proinflammatory cytokine IL-1β." (PMID 38651925, 2024). "In the early stage of a viral infection, IL-1β and IL-18 promote the activity of CD8+ T cells and induce antibody secretion, thus playing protective roles; however, when overproduced, these cytokines destroy benign tissues." (PMID 39203394, 2024). "Staining with antibody against IL-1β and NP revealed that infection with RVFV-NSsRM resulted in reduced IL-1β accumulation in both liver and spleen tissues compared with WT virus infection." (PMID 39213434, 2024). "Pro-IL-1β is highly upregulated when the cells were stimulated upon viral infection or cellular stress, mediated NF-κB activation." (PMID 39038050, 2024). "During viral infections or inflammation, the increased expression of pattern recognition receptors (PRRs) and Toll-like receptors (TLRs) leads to enhanced IL-1β expression." (PMID 39651347, 2024).
viral infection (continued). "IL-6 production is triggered in response to bacterial and viral infections and other cytokines such as IL-1β, TNF, and IFN-γ." (PMID 38362301, 2024). "ZBP1-mediated PANoptosis was characterized by NLRP3 inflammasome activation with LDH and IL-1β release during viral infection." (PMID 39850894, 2024). "Protein concentrations of interferons (IFN-β, IFN-λ, and IFN-γ) and pro-inflammatory cytokines (IL-1β, IP-10, and IL-6) were higher upon virus infection in all cultures." (PMID 37072183, 2023). "Numerous studies have demonstrated significant inflammasome activity in viral infection models, including the activation of caspase-1 and the secretion of interleukin-1β (IL-1β)." (PMID 37704783, 2023). "Environmental triggers such as viral infection or danger signals are recognized by monocytes, resulting in the activation of inflammatory pathways and over-production of cytokines, including IL-1β, IL-6, IL-18, and TNF." (PMID 38124139, 2023). "We found that both doses significantly reduced the release of inflammatory cytokines (TNFα, IL-6, and IL-1β), induced by virus infection." (PMID 37108306, 2023). "IL-1β is released rapidly in response to bacterial and viral infections and helps stimulate early innate immune responses." (PMID 36670458, 2023). "Proteins encoded by IER3 are stimulated by multiple stressors, including viral infection and IL‐1β, and play a complex role in cell cycle regulation and apoptosis for multiple cell types." (PMID 37078407, 2023). "Both in vivo and in vitro experimental data demonstrated that viral infection induces innate immunity, with mRNA expression levels of two key inflammatory factors, interleukin-1β (IL-1β) and IL-18, significantly upregulated." (PMID 37063902, 2023). "The results showed that phillyrin treatment alleviated pneumonia induced by virus infection and significantly ameliorated the upregulation of multiple pro-inflammatory cytokines and chemokines (e.g., IL-1β, CXCL1, CCL3, CCL2, CCL5 and so on) in BALF." (PMID 37957672, 2023). "We found that the inhibitory effect of HMPV on LPS-triggered IL-1β mRNA expression became detectable between 6 and 18 hours post viral infection." (PMID 37435074, 2023). "We highlight that only THP-1 cells showed a significant increase in IL-1β production after viral infection, while CaLu-3 cells were completely unaffected." (PMID 37986089, 2023). "Acute tissue injury or viral infection can activate immune cells, and IL-1β is mainly derived from activated macrophages, and can activate neutrophils, inducing a shock-like state in animal models." (PMID 37836540, 2023). "In the case of viral infections, elevated levels of various inflammatory cytokines, including IL-1β, IL-6, IL-7, IL-17, IFN-γ, IL-8, TNFα, and GM-CSF are observed, alongside IL-4 and IL-5." (PMID 37692890, 2023). "Among these genes, the expression of the inflammatory downstream mediators IL-10, IL-1B, IL-6, and IL-8 was significantly reduced, an interesting finding that was rarely observed in viral infection." (PMID 37134013, 2023). "Previous studies have demonstrated that macrophages are attributed to IL-1β production during viral infections." (PMID 36503883, 2022). "For example, platelet-derived cytokine IL-1β release in response to bacterial LPS or viral infection leads to increased phagocytosis of bacteria and further IL-1β production by macrophages." (PMID 36463349, 2022). "As expected, after viral infection, the amount of mature IL-1β released from samples expressing NLRP3-GFP was similar to that in cells expressing either NLRP3 or Flag-NLRP3." (PMID 35062292, 2022). "In response to viral infection, macrophages secrete large amounts of cytokines, including IL-1β, to inhibit the replication of viruses." (PMID 36326277, 2022). "Proinflammatory cytokines, including TNF-α and IL-1β, can be robustly induced after viral infection." (PMID 36359059, 2022).
viral infection (continued). "It is well known that the damage to endothelial cells after viral infection and/or activation of endothelium by pro-inflammatory cytokines, such as IL-1β, IL-6, IFN-γ, IL-8 and TNF-α induces platelets and monocyte aggregation in the vascular wall." (PMID 36291697, 2022). "IL-1β and IL-12 are key pro-inflammatory cytokines important for the fighting against bacterial and viral infection." (PMID 36131943, 2022). "The pro-inflammatory cytokine interleukin-1beta (IL-1β) has been known to have a protective function against a variety of bacterial, fungal, and viral infections." (PMID 36671206, 2022). "Respiratory Syncytial Virus (RSV), a viral infection associated with particularly severe outcomes in young children, has been shown to activate the NLRP3 inflammasome, resulting in secretion of IL-1β." (PMID 36298668, 2022). "As a result, viral infection can trigger multiple signaling cascades leading to the release of multiple cytokines, including the IL-1 family cytokines IL-1β and IL-18, and type I and type III interferons (IFNs)." (PMID 36110852, 2022). "Cytokines are crucial in combating viral infection and are involved in the regulation of immune and inflammatory responses, including interleukin 1β (IL-1β), interleukin-6 (IL-6) and tumor necrosis factor alpha (TNF-α)." (PMID 36146669, 2022). "CCL5) that are known to respond to dsRNA, proinflammatory cytokines IL-6 and IL-8 that were shown to be suppressed by sEVs from TVV positive T. vaginalis, and IL-1β, a proinflammatory factor during viral infection." (PMID 35602021, 2022). "It was associated with higher neutrophil recruitment by increased levels of CXCL1/2, CXCR2, and interleukin 1β (IL-1β) at a later stage of viral infection." (PMID 36005818, 2022). "In the acute inflammatory response phase to viral infection, an early increase in serum IL-1β and TNF-α levels are observed within the first 30 min, followed by a rise in IL-6 levels." (PMID 35888173, 2022). "During viral infection, two principal mechanisms occur to modulate ferritin levels, iron availability, and inflammatory cytokines levels: IL-1β and IL-6." (PMID 36613462, 2022). "Such an effect on iron homeostasis can be related to the ability of Lf to chelate free iron and downregulate pro-inflammatory cytokines, such as IL-1β and IL-6, thus boosting anti-oxidant and anti-inflammatory host response to viral infection." (PMID 36297546, 2022). "IL-1β is also an endogenous pyrogen prominent during the febrile phases of some viral infections and induces the production of prostaglandin E2 in the hypothalamus, resetting the hypothalamic thermostat to fever." (PMID 35173184, 2022). "Activation of the inflammasome (e.g., as a result of viral infection) recruits caspase-1, which subsequently converts pro-IL-1β into mature IL-1β by removing the N-terminal 117 residues." (PMID 35671825, 2022). "During viral infection, pro-IL-1β is cleaved by inflammasome-derived caspase-1 and become a mature product." (PMID 35464987, 2022). "Numerous studies have demonstrated that acute viral infections can induce M1 macrophage polarization, which results in the release of pro-inflammatory factors, such as IL-1β, IL-6, and iNOS." (PMID 36147321, 2022). "The involvement of the CLEC5A signaling in the activation of NLRP3 inflammasome and resulting IL-1b production have been already described during viral infections with DV and JEV as well as in the infection with L. monocytogenes." (PMID 35252461, 2022). "The AIM2 gene is related to the hyperinflammatory manifestation of MIS-C patients since triggers caspase-1 and unleashes pro-inflammatory cytokines such as IL-1β and IL-18,19 which are also involved in the innate immune response to viral infections." (PMID 35770252, 2022). "The pro-inflammatory activity of astrocytes can be induced to high levels by IL-1β and TNFα and viral infections, e.g., HIV, to facilitate an immune response." (PMID 35448516, 2022).